STAT3 (signal transducer and activator of transcription 3)
Diseases named in the same sentence as STAT3 in open-access papers (continued):
Sharing a sentence is not in itself a finding about the gene and the disease.
renal fibrosis (continued). "Evidence has demonstrated that interfering with IL-6 trans-signaling could attenuate renal fibrosis via suppressing STAT3 activation while inhibiting the recruitment of macrophages." (PMID 35784347, 2022). "Experimental evidence suggests that inhibition of JAK/STAT (in particular, JAK2/STAT3) may suppress renal fibrosis and thereby protect renal function." (PMID 34335747, 2021). "Moreover, STAT3 is activated as a potential transcription factor, which mediates the stimulation of renal interstitial fibroblasts and the progression of renal fibrosis in unilateral ureteral obstruction (UUO) mice." (PMID 33806080, 2021). "In conclusion, our data suggest that SK may effectively inhibit renal fibroblast activation and renal fibrosis in UUO mice by regulating the JAK2/STAT3 signaling pathway." (PMID 33407391, 2021). "Therefore, this study investigated the inhibitory effects of STAT3 decoy ODNs on autophagy regulation in an animal model of renal fibrosis." (PMID 33806080, 2021). "Low-dose IL-17A administration could suppress renal fibrosis and inflammation through inhibiting STAT3." (PMID 34199002, 2021). "Inhibition of Fyn attenuated renal fibrosis through inhibiting p-STAT3." (PMID 34199002, 2021). "In addition, the role of STAT3 in UUO was further verified by S3I-201, a STAT3 inhibitor which inhibited STAT3 phosphorylation and attenuated renal fibrosis." (PMID 34199002, 2021). "Moreover, receptor binding is activated in the JAK/STAT pathway, and STAT3 activation mediates the stimulation of renal interstitial fibroblasts and the progression of renal fibrosis in UUO mice." (PMID 33806080, 2021). "Suppression of STAT3 in renal TECs or macrophages inhibits renal fibrosis." (PMID 34831283, 2021). "Recent evidence indicates that signal transducer and activator of transcription 3 (STAT3) might mediate the process of renal fibrosis, which could induce the expression of hypoxia-inducible factor-1α (HIF-1α)." (PMID 34193173, 2021). "Recent studies using db/db mice have shown that the activation of the signal transducer and activator of transcription 3 (STAT3) pathway in mesangial cells by IL‐6 leads to the secretion of fibronectin (FN), which, in turn, promotes renal fibrosis and sclerosis." (PMID 33043579, 2020). "Pterostilbene, also mentioned in this review, suppresses the activation of TGF-β1/Smad3 and proto-oncogene tyrosine-protein kinase Src/Signal transducer and activator of transcription 3 (Src/STAT3) signaling pathway as to decrease sUA level and alleviate renal fibrosis in hyperuricemic mice." (PMID 33568990, 2020). "Seo and colleagues focused their attention on STAT3 signaling in renal fibrosis, and they have found Fyn, a member of the Src family of kinases, could be the upstream activator of STAT3." (PMID 33335643, 2020). "We reported that Fyn deficiency inhibits renal fibrosis by reducing the expression of phospho-STAT3, but not of Smad3." (PMID 32120837, 2020). "Meanwhile, we also found that the increased protein level of collagen I induced by UUO surgery was partially reversed by knockdown miR-155-5p, implying that STAT3 may mediate renal fibrosis." (PMID 32587662, 2020). "Conclusively, these results suggest that the deletion of Akt1 may contribute to renal fibrosis via induction of the TGFβ1/STAT3 pathway in a murine model of UUO." (PMID 33299873, 2020). "Altogether, our findings highlight a miR-155-5p/SOCS/STAT3 axis in the pathogenesis of renal fibrosis, which may provide promising therapeutic targets for clinical prevention of this disease." (PMID 32587662, 2020).
renal fibrosis (continued). "Our present study shows an additional potential interplay of STAT3 and PPARγ in renal fibrosis, as STAT3 was activated in kidneys of untreated TGF-β1 transgenic mice, but STAT3 activation was absent in kidneys of TGF-β1 transgenic mice chronically treated with pioglitazone." (PMID 31277592, 2019). "As in the case of Prdx2-mediated Stat3 regulation, further studies are needed to determine whether PrdxV modulates renal fibrosis by peroxidase-mediated redox signaling in regulating TGF-B-induced Stat3 activation." (PMID 31217524, 2019). "Here, we aimed to study whether the chronic administration of PPARγ agonist pioglitazone could influence renal EGR-1, STAT3 and AP-1 expression, and ameliorate renal fibrosis in TGF-β1 overexpressing mice." (PMID 31277592, 2019). "Furthermore, STAT3 activation mediates the stimulation of renal interstitial fibroblasts and the progression of renal fibrosis in UUO models." (PMID 30177595, 2018). "STAT3 activation involved in renal fibrosis had been reported." (PMID 28693431, 2017). "miR-199a-3p as an pro-fibrotic factor involves in renal fibrosis by SOCS7/STAT3 axis." (PMID 28680559, 2017). "Previous study has proved STAT3 inhibitors ameliorate renal fibrosis." (PMID 28680559, 2017). "On the other hand, a receptor‐independent inducer of gp130/STAT3 pathway, hyper‐IL‐6, is capable of consistently inducing in vitro pluripotency transcription factors, Nanog and c‐Myc, and later on Oct4, and preventing renal fibrosis in vivo." (PMID 28297566, 2017). "Selective inhibition of Stat3 by ectopic expression of Prdx5 could be a therapeutic target in TGF-β induced renal fibrosis." (PMID 26872211, 2016). "Among non-canonical TGF-β/Smads pathway, activation of Stat3 has also been implicated in renal fibrosis." (PMID 26872211, 2016). "Consequently, we suggested that Prdx5 plays a role as anti-fibrotic effector in the pathogenesis of renal fibrosis, and its regulation mechanism was through by inhibition of Stat3 activation." (PMID 26872211, 2016). "Therefore, SirT1, STAT3, Twist1 and Cpt1a may represent useful targets for the prevention of renal fibrosis." (PMID 35408745, 2022). "However, mTOR/STAT3 ODN suppressed UUO-induced renal fibrosis and inflammation." (PMID 35164031, 2022). "It is concluded that JAK/STAT3 signaling may promote the repair process of renal fibrosis in UUO." (PMID 34199002, 2021). "Additionally, the roles of IL-6 were reported in several kidney diseases and targeting IL-6 could protect against renal fibrosis by suppressing STAT3 activation." (PMID 34884542, 2021). "Furthermore, p-STAT3 expression was increased in UUO-induced renal fibrosis." (PMID 33806080, 2021). "The study demonstrated that hirudin effectively reduces ferroptosis and renal fibrosis in UUO rats and RSL3-induced HK-2 cells, while decreasing protein levels related to the STAT3/NLRP3 signaling pathway." (PMID 40298655, 2025). "Treatment with the STAT3 activator colivelin reversed this effect, further verifying that hirudin inhibits ferroptosis by regulating the STAT3/NLRP3 signaling pathway in renal fibrosis." (PMID 40298655, 2025). "This study evaluated the effects of CA on renal fibrosis, lipid deposition and lipid metabolism by constructing in vitro and in vivo models of DKD, and detected the improvement of Notch1 and Stat3 signaling pathways." (PMID 38952291, 2024).
renal fibrosis (continued). "During renal fibrosis, discoid domain receptor 1 (DDR1) has been found to promote renal inflammation and fibrosis by promoting the phosphorylation of BCR and STAT3." (PMID 36747131, 2023). "Astaxanthin significantly reduced renal fibrosis through SMAD2, STAT3 (representing signal transducer and activator of transcription 3), Akt, Snail and β-catenin pathways inhibition." (PMID 37762322, 2023). "At the same time, STAT3 can promote the high expression of α-SMA and fibronectin, which promote the development of renal fibrosis in CKD, a process that can be alleviated by the specific STAT3 signaling pathway inhibitors AG490 or TSA." (PMID 36148005, 2022). "It has also been reported that rhein can inhibit the process of renal fibrosis by regulating TGF-β, SIRT3 or STAT3 signals, apoptosis or autophagy of renal tubular cells." (PMID 35408745, 2022). "Interestingly, unlike PP1 inhibiting Src to block Smad3 and STAT3 signaling pathways, Fyn-mediated renal fibrosis is mediated by the non-Smad signaling pathway, that is, caused by activation of STAT3, and Smad3 and AMPK signaling transduction are not essential in this process." (PMID 35883540, 2022). "Our recent studies have shown that blockade of HDAC6 with ACY-1215 also attenuated renal fibrosis through a mechanism involving the inactivation of TGFβ1/Smad3, EGFR/AKT, STAT3 and NF-κB signaling pathways in a murine model of UUO injury." (PMID 35559244, 2022). "In UUO-induced renal fibrosis mice model, the HDAC8 inhibitor, PCI34051, inhibited Smad3, STAT3, β-catenin and Snail expressions and activated BMP7 and Klotho renal protective protein expressions." (PMID 35250597, 2022). "The results of the Western blot analysis showed increased expressions of inflammatory-related transcription factor (p-STAT3), inflammatory cytokines (IL-1β, TNF-α), NGAL, and fibrosis-related markers (α-SMA, fibronectin) in UUO-induced renal fibrosis." (PMID 36232665, 2022). "In the latest research report, dasatinib alleviates renal fibrosis by inhibiting Src, c-Abl, STAT-3, and NF-κ B signaling in the UUO-induced renal fibrosis model." (PMID 35883540, 2022). "Our results showed that SK reduced extracellular matrix (ECM) and α-smooth muscle actin (α-SMA) expression both in vitro and in vivo and attenuated renal fibrosis and the pathological lesion degree after UUO, suppressing JAK2/STAT3 activation." (PMID 33407391, 2021). "Our results suggested that IL-6 affects renal fibrosis by acting on IL6ST in DN progression, and the IL6ST/STAT3/NF-kB signaling pathway plays an important role in DN progression." (PMID 33995063, 2021). "IL-22 binds to kidney IL-22R1 to activate STAT3, JAK and other signaling pathways, and regulate renal fibrosis through the ERK, Akt, and p38MAPK signaling pathways." (PMID 34295334, 2021). "Several previous publications have highlighted that SKI retarded renal fibrosis by inhibiting levels of interleukin-6, interleukin-1β, and TNF-α and modulating TGF-β1/Smad3 and JAK2/STAT3 signaling pathways." (PMID 35002735, 2021). "In conclusion, long-term administration of ISO at all three dosages (10, 20, and 40 mg/kg) effectively improved STZ-induced acute renal injuries in DN model rats via improving renal fibrosis, oxidative stress, and inhibiting JAK2/STAT3 signaling pathway." (PMID 34784849, 2021). "Thus, JAK2/STAT3 could be a direct therapeutic target of SK for renal fibrosis." (PMID 33407391, 2021). "Pathologic activation of Stat3 and ERK1/2 by phosphorylation (p-Stat3 and p-ERK1/2) occurs in organ fibrosis, including renal fibrosis." (PMID 31727005, 2019).
renal fibrosis (continued). "Since MMP-2 is a target gene of STAT3, JAK2/STAT3 blockade reduced MMP-2 expression and renal fibrosis in the developing kidney with obstruction." (PMID 31846485, 2019). "Oral administration of PPARγ agonist pioglitazone significantly reduces TGF-β1-driven renal fibrosis, via the attenuation of EGR-1, STAT3 and AP-1." (PMID 31277592, 2019). "Weathington confirmed that IL-22, the main effect molecule of Th22 cell, can bind to the IL-22RA receptor, activating JAKI–STAT1 and STAT3 pathways, regulating Akt, ERK, JNK and p38 signal, thus participating in the regulation of renal fibrosis." (PMID 29708439, 2018). "Since STAT3 has been implicated in the regulation of tubulointerstitial fibrosis following UUO and is a known HDAC target, these findings suggest HDACi may also decrease renal fibrosis by decreasing STAT3 expression and signaling in this model of chronic kidney disease." (PMID 23052657, 2013). "Based on these insights, we speculate that HDAC11 may similarly act as a molecular switch in the STAT3 signaling cascade, linking HDAC11 activation to the development of EMT and renal fibrosis." (PMID 41275091, 2025). "Its renoprotective activities are via the RhoA/Rho‐associated coiled‐coil‐containing kinase signaling pathway, suppressing renal fibrosis in HG‐induced glomerular MCs, upregulating Janus Kinase‐2 (JAK2)/STAT3 and Nrf‐2/HO‐1, TGF‐β1/Smad/ECM, and TGF‐β1/CTGF/ECM signaling cascades." (PMID 41019174, 2025). "The effect of S3I‐201, a STAT3 inhibitor, was assessed in UUO‐induced renal fibrosis mouse model." (PMID 39665319, 2025). "Furthermore, EZH2 promoted renal fibrosis by inhibiting PTEN expression and activating STAT3 and ERK1/2 phosphorylation." (PMID 38929505, 2024). "In conclusion, this experimental study shows that β-elemene reduces renal fibrosis by targeting JAK2/STAT3, Smad3, and Myd88 signaling factors and may serve as a potent inhibitor of STAT3 and Smad3 in the future." (PMID 35628363, 2022). "In this study, we demonstrate that pharmacological and genetic inhibition of HDAC4 attenuates renal fibrosis and suppresses the molecular mechanisms leading to renal fibrosis, including the pEMT, fibroblast activation, and activation of the TGF-β1/Smad3, STAT3, and ERK1/2 signaling pathways." (PMID 35847036, 2022). "In conclusion, ISO at all three dosages could efficiently improve the renal injury induced by STZ via ameliorating renal fibrosis, oxidative stress, and inhibiting JAK2/STAT3 signaling pathways in the DN rats." (PMID 34784849, 2021). "Therefore, this study investigated the role of STAT3 decoy oligonucleotides (ODN) in autophagy and their effect in terms of preventing renal fibrosis in kidney disease." (PMID 33806080, 2021). "In this study, we use synthesized STAT3 decoy oligonucleotides (ODN), which were injected into the tail veins of unilateral ureteral obstruction (UUO) mice, to explore the regulation of autophagy in UUO-induced renal fibrosis." (PMID 33806080, 2021). "This study suppressed the expression of the STAT3 transcription factor synthesized to STAT3 decoy ODNs, which were injected into the tail veins of UUO mice, to explore the regulation of autophagy in UUO-induced renal fibrosis." (PMID 33806080, 2021). "Previously, S3I‐201, an inhibitor of STAT3 phosphorylation, was shown to inhibit renal fibrosis in a mouse model, but its mechanism was not clarified completely." (PMID 33112058, 2020). "In the progression of renal fibrosis, TGF-β1 signaling promotes the deposition of the extracellular matrix via activating transcriptional factors either Smad (such as Smad2/3/4) or STAT (such as STAT3) family." (PMID 32587662, 2020). "Our study demonstrated that Sirt1 inhibits renal fibrosis at least partially by inhibiting AT1R and NF-κB expression, and previous studies also supported that Sirt1 inhibits renal fibrosis by inducing COX2, deacetylating Smad3 and STAT3." (PMID 27659793, 2016).
renal fibrosis (continued). "Studies have proved that the phosphorylation of STAT3 in renal tubular cells of type 1 diabetic C57BL/6 mice was enhanced, whereas the diabetic mice treated with STAT3 inhibitor S3I-201 resulted in the improvement of renal fibrosis, inflammatory response, and renal function." (PMID 37635867, 2023). "Mechanistically, several preliminary studies have revealed that SKI alleviated CKD and renal fibrosis by inhibiting pro-inflammatory cytokines such as interleukin-6, interleukin-1β, and tumor necrosis factor-α (TNF-α) expression and modulating TGF-β1/Smad3 and JAK2/STAT3 signaling pathways." (PMID 35002735, 2021). "Furthermore, long-term administration of ISO could ameliorate excessive oxidation stress, down-regulate the expression levels of renal fibrosis- and inflammation-related factors, as well as inhibit the JAK2/STAT3 signaling pathway." (PMID 34784849, 2021). "Moreover, our previous studies demonstrated that pharmaceutical and genetic blockade of EGFR leads to dephosphorylation of STAT3 and ERK1/2 and attenuation of renal fibrosis; pharmaceutical inhibition of EGFR/ERK signaling is associated with reduction of peritoneal fibrosis." (PMID 31727005, 2019). "And this could be done by inhibiting the activation of STAT3 and the production of STAT3-dependent MMP-9; these findings indicated that the JAK-STAT signaling pathway was involved in the mechanism of MSCs preventing renal fibrosis." (PMID 30766607, 2019). "Furthermore, a chronic study in DN model rats revealed that long-term treatment of ISO could improve the diabetic characteristics and renal functions in acute DN rats through ameliorating renal fibrosis, oxidative stress, and inhibiting JAK2/STAT3 signaling pathways." (PMID 34784849, 2021). "We therefore wanted to reaffirm whether, among the many noncanonical TGF-β signaling pathways, activation of Stat3 by knockdown of PrdxV is one of the signaling pathways of renal fibrosis induced by UUO, and if so, whether any upstream molecules are involved in the activation of Stat3." (PMID 31217524, 2019).